FYB2 (FYN binding protein 2)
Description:
Adapter protein that plays a role in T-cell receptor (TCR)- mediated activation of signaling pathways. Required for T-cell activation and integrin-mediated T-cell adhesion in response to TCR stimulation.
Synonyms: ARAP; C1orf168; RP4-758N20.2; FLJ43208
Tractability: Antibody: its Gene Ontology location is reachable by antibodies, with medium confidence.
Gene: Protein-coding gene on chromosome 1 (56,718,789 to 56,819,696, reverse strand). Ensembl gene ENSG00000187889.
Subcellular location: Membrane raft
Subcellular location (Human Protein Atlas): Mid piece; Perinuclear theca; Principal piece
Gene Ontology:
Molecular function: protein binding
Biological process: cell adhesion mediated by integrin; T cell receptor signaling pathway; integrin-mediated signaling pathway; protein localization to plasma membrane
Cellular component: immunological synapse; membrane raft; plasma membrane
Genetic constraint (gnomAD): Loss-of-function variants: 62 observed, 66.48 expected, observed/expected ratio (o/e) 0.93, 90% interval 0.76 to 1.15. The upper end of that interval is the gene's LOEUF score, 1.15, which puts it in group 5 of 6, group 1 being the genes least tolerant of losing a copy. Missense variants: 711 observed, 720.16 expected, observed/expected ratio (o/e) 0.99, 90% interval 0.93 to 1.05. Synonymous variants: 239 observed, 252.19 expected, observed/expected ratio (o/e) 0.95, 90% interval 0.85 to 1.05.
Homologues: Orthologues: chimpanzee FYB2 (98% identical), macaque FYB2 (92% identical), pig FYB2 (69% identical), rabbit FYB2 (65% identical), guinea pig FYB2 (59% identical), mouse Fyb2 (58% identical), rat Fyb2 (56% identical), dog FYB2 (29% identical), zebrafish si:ch211-188c16.1 (12% identical), zebrafish si:ch211-232i5.3 (4% identical). Paralogues in human: FYB1 (21% identical), PRAM1 (15% identical).